MYD88 (MYD88 innate immune signal transduction adaptor)
Diseases named in the same sentence as MYD88 in open-access papers (continued):
Sharing a sentence is not in itself a finding about the gene and the disease.
infection (continued). "In contrast, MyD88-dependent protection from lethal VSV infection occurred independent of type I interferon, correlated with the recruitment of monocytes to the site of infection and was dependent on IL-1R1 signaling." (PMID 19079579, 2008). "In contrast, in Myd88−/− macrophages, MAPK activation in response to WT L. pneumophila was delayed, detectable at 60 minutes, peaked at 120 minutes, and sustained for at least 4 hours post infection." (PMID 19043549, 2008). "The genetic absence of MyD88 resulted in enhanced pulmonary pathology and greater than 90% mortality by day 6 post-infection." (PMID 19079579, 2008). "Previous observations showed that infection with a low dose of L. pneumophila allowed for the detection of T4SS-dependent NF-κB activation in macrophages lacking either MyD88 or Nod1." (PMID 19043549, 2008). "We found that wek knock-down in MyD88+ cells improved fly survival after seven days of infection, albeit not significantly, and it did not rescue climbing, which could be explained by DAN loss." (PMID 39946503, 2025). "We found that MyD88 levels were constant from d3 until d9 post-infection, irrespective of whether the culture was infected with WT or UL88-STOP TB40/E." (PMID 40638072, 2025). "Interestingly, adult-restricted knock-down of Toll-1 in MyD88+ cells improved fly survival after seven days of infection (albeit not significantly compared to infected genetic controls)." (PMID 39946503, 2025). "Additionally, the expression of MyD88, NF-κB p65, iNOS, and Arg-1 was significantly elevated in the E. granulosus group, confirming that GHSR-/- mice exhibited milder infection and a lower inflammatory status, further supporting the conclusion that GHSR deficiency alleviates E. granulosus infection." (PMID 40065480, 2025). "As this upregulation occurred quickly after low MOI infection, when the majority of cells in the culture are not infected, we hypothesized that MyD88 upregulation may not require virus replication." (PMID 40638072, 2025). "Furthermore, as observed upon treatment with purified VCC, V. cholerae-induced cytokine production was also attenuated upon infection in the neutrophils, isolated from the TLR1-/-, MyD88-/- and C3H/HeJ (TLR4-defective), mice as compared to those from the wild type mice." (PMID 40184418, 2025). "This is consistent with a role for UL88 in HCMV spread to MyD88-expressing cells during a low MOI infection and is inconsistent with a role for UL88 production of defective viral particles or genomes (which would be unaffected by UV treatment) in modulation of MyD88 expression." (PMID 40638072, 2025). "Infection did not influence the overall frequency of ILC in either Myd88+/+ or Myd88-/- mice." (PMID 40299872, 2025). "However, by d12, WT TB40/E had reduced MyD88 levels closer to those observed without infection than at d3 post-infection." (PMID 40638072, 2025). "Ethacridine’s predicted targets include MyD88, NF-κB, and MAPKs, suggesting it could temper TLR/NLR signaling to a moderate level—enough for infection control but not so much as to cause collateral tissue damage." (PMID 41150817, 2025). "Similar to the infection studies, there was negligible secretion of proinflammatory cytokines by ΔTLR2 and ΔMyd88 cells, confirming that PE18 and PPE26 elicit production of proinflammatory cytokines by murine macrophages mediated by the innate immune receptor TLR2 and adapter Myd88." (PMID 39949767, 2025). "pDCs are resistant to infections by many viruses but engulf viral particles or material derived from infected cells and route these cargos to dedicated endosomes to trigger the TLR7/9-to-MYD88-to-IRF7 signaling pathway, which activates the promoters of all IFN-I/III genes." (PMID 38777879, 2024).
infection (continued). "Moreover, infection with S. aureus reportedly elevates IL-22–derived γδ T cells in mechanically injured skin, and these cells have been identified as protective against S. aureus reinfection by producing TNF-α and IFN-γ via the TLR2/MyD88 signaling pathway." (PMID 38319737, 2024). "Our results show that susceptibility to infection of myd88-/- larvae injected with HD of WT-GFP was comparable to that of WT larvae, as only a very slight, but no significant increase of bacterial burden was observed in myd88-/- larvae by 24 hpi." (PMID 37155695, 2023). "Taken together, our results suggest that MyD88 signalling is not required for the innate immune response against L. pneumophila infection in the zebrafish larvae, corroborating what has been observed in human cell infection models." (PMID 37155695, 2023). "Also, as observed in human infections, the adaptor signalling molecule Myd88 is not required to control disease in the larvae." (PMID 37155695, 2023). "Mayotte 2008 infection also induced upregulation of specific genes such as CAPS1, MYD88, and TLR3." (PMID 37306630, 2023). "The recognition of PAMPs and DAMPs determines the recruitment of TIR domain-containing adaptor proteins (e.g., MyD88 and TRIF) with the subsequent activation of NF-κB, IRFs, or MAP kinases, thus, modulating the expression of cytokines, chemokines, and type I IFNs to counteract infection." (PMID 35203343, 2022). "To determine whether MyD88 was also required for RV-specific CD8 T cell responses, we analyzed total and RV-specific effector CD8 T cells in the MLN of adult mice seven days post-infection." (PMID 35464475, 2022). "Hence, we thus focused on intestinal immune-related enzymes, intestinal antioxidant capacities, and physical barrier functions, regulated via the TLR4/MyD88/NF-kB and MLCK signaling pathway by using Songpu mirror carp with AKG supplementation after infection with A. hydrophila." (PMID 34220849, 2021). "Accordingly, here, we attempted to address whether MyD88- and TRIF-mediated TLR4-signaling is dependent either on Neu1 or Siglec-E or both together through their action on the sialic acids of TLR4 during this infection." (PMID 33763070, 2021). "However, at an early stage of infection (3 hpi), it has been shown that the recruitment of leukocytes towards an Mm infection site is not dependent on Myd88-mediated signalling." (PMID 33559740, 2021). "In vitro infection of MyD88-/- LP cells with the different parasite strains failed to elicit IL-12." (PMID 34597344, 2021). "Thus, the results above from in-depth mechanistic experiments demonstrated that MIR337-3p targeted/depressed upstream TLR4/MYD88 and STAT3 signaling and the downstream VDR antimicrobial pathways of CYP27B1/DEFB4A/CAMP, leading to an enhanced mycobacterial entry/infection and growth." (PMID 34912331, 2021). "If microglia normally respond to IL-33 earlier in infection, our results indicate that astrocyte responses to IL-33, or additional MyD88-dependent signals, may compensate for the lack of il1rl1-signaling in microglia." (PMID 33108405, 2020). "Furthermore, while mice lacking either MyD88 or IL12p40 succumb rapidly to infection, mice that lack Myd88 specifically in DCs or macrophage lineages do not, indicating that there are other factors and cytokines that regulate IL12 and IFNγ secretion." (PMID 33178630, 2020). "Overall, these studies suggest that TRIF plays a moderate role in the outcome of the infection by WT bacteria, unlike MyD88, and could be key to determine the outcome of both the acute phase and chronic kidney colonization in mice." (PMID 32790743, 2020). "We also investigated the interplay between nicotine, TLR2 and TLR4 for their reported role in infection by gram-negative and -positive bacterial infection, and subsequent effect on MyD88 signaling, inflammatory response, and bacterial load in infected macrophages." (PMID 33212859, 2020).
infection (continued). "These factors may contribute that some positive infection individuals show higher expression of MyD88 but not reach significant level." (PMID 32477927, 2020). "We also found that deletion of signaling molecules that act upstream of type I IFN production including multiple TLRs, RIPK2, cGAS/STING, or MAVS pathways, did not increase BMDM fusion during infection while control BMDMs lacking MyD88 and TRIF or IFNAR1 extensively fused." (PMID 32150572, 2020). "IL-1α has only recently emerged as an alarmin that rapidly initiates the production of pro-inflammatory mediators in a MyD88-dependent manner, thus promoting recruitment of neutrophils and macrophages to the site of infection as well as their activation independent of TLR signaling pathways." (PMID 30846984, 2019). "While rapid type I IFN production in pDCs was observed following infection with mouse hepatitis virus (MHV), a betacoronavirus, its induction was abrogated in TLR7−/− or MyD88−/− MHV-infected mice, indicating that MHV-mediated type I IFN induction in pDCs was triggered via the TLR7/MyD88 pathway." (PMID 30854373, 2019). "Thus, despite a more than 1.5-log higher bacterial burden, Myd88−/− mice generated only a weak granulomatous reaction to NMII in the liver, indicating that MyD88 signaling is essential to attract leukocytes to the sites of infection." (PMID 30800124, 2019). "In response to IV infection TNFα promotes the secretion of the antiviral cytokine families: type I, II, and III IFNs through upregulating RIG-I and toll-like receptor 3, Myeloid differentiation primary response 88 (MyD88), TIR-domain-containing adapter-inducing interferon-β (TRIF), and IRF7 genes." (PMID 30250466, 2018). "In this study, we examined the regulation of PGRP-LE (Imd pathway), MyD88 (Toll pathway), Wgn (Jnk pathway), Dome (Jak/Stat pathway), Daw (Activin, TGFβ pathway), and Dpp (BMP, TGFβ pathway) genes in D. melanogaster larvae responding to infection with S. carpocapsae symbiotic or axenic nematodes." (PMID 29419764, 2018). "However, higher levels of the L-arginine transporters Cat2B and Cat1 were detected in the absence of Myd88 signaling during infection but were not altered following let-7e inhibition." (PMID 30555476, 2018). "Although previous studies, in different models of infection, have shown the importance of MyD88 signaling intrinsic to T cells, none of those works has identified the receptor upstream the MyD88 adaptor molecule playing a determinant role for the Th1 response in vivo." (PMID 28895840, 2017). "In addition, we show Ntan1, which was down-regulated in WT cells, but was not regulated in MyD88-/- BMMs upon infection." (PMID 28445535, 2017). "Our data indicate that MyD88 expression in MO alone is not sufficient to activate an appropriate ILC3 response after infection, which is consistent with the notion that these cells are rather refractory to TLR stimulation, at least under homeostatic conditions." (PMID 28520792, 2017). "Although not beneficial for host survival, this may enhance infection and benefit tick transmission of pathogens, since MyD88 has been shown to restrict the flaviviruses West Nile virus (WNV) and Japanese encephalitis virus (JEV), in mammalian cells." (PMID 28202075, 2017). "Enhanced infection was inversely seen with dilution factors of anti-DenV2 sera obtained from BL/6, TLR2 KO, and MyD88 KO mice, which indicates that anti-DenV2 sera from BL/6, TLR2 KO, and MyD88 KO mice could increase the infectivity of DenV2 and DenV4 in FcγR-bearing macrophages." (PMID 29285314, 2017). "Similarly to KIM6, infection by the ΔphoP mutant did not reduce IFN-β expression by Myd88−/− BMDMs, indicating that IFN-β secretion by the intracellular survival mutant is also MyD88 independent." (PMID 28847850, 2017).
infection (continued). "The lack of direct IL-18R signaling in T cells, but not of IL-1R, phenocopied the absence of the MyD88 pathway, indicating that IL-18R is a critical MyD88-upstream pathway involved in the establishment of the Th1 response against an in vivo infection, a presently controvert subject." (PMID 28895840, 2017). "SK3842 infection raised Nod1 and repressed MyD88 levels in differentiated Caco-2 but did not have any significant effect on Nod1 and MyD88 in SC-rich CD44high cells from infected culture, further confirming that only non-stem cells are responsive to SK3842 invasion." (PMID 28300841, 2017). "The absence of MyD88, a molecule that acts downstream of numerous canonical pathway receptors, led to a defect in germinal center formation and a reduction of latency establishment early after infection with MHV68." (PMID 27582728, 2016). "However, the more critical distinction is likely the fact that our study employed a live infection, as opposed to administration of LPS or IL-1, which more specifically engage MyD88-dependent signal transduction mechanisms." (PMID 26790027, 2016). "Interestingly, although MyD88 was required for moDC generation during persistent LCMV infection, the requirements were indirect and MyD88 sensing of infection formed a foundation to induce expression of additional factors that then led to iregDC differentiation." (PMID 26808628, 2016). "The number of activated (CD44+), Myd88-/- vs. Myd88+/+ 1807 cells was not reduced at day 7 post-vaccination (burst of T cell expansion), at day 35 (contraction of T cells) and at day 4 post-infection (recall to the lung)." (PMID 27542117, 2016). "Importantly, dissemination of D39Δcps to the circulation was only found in Myd88-/- mice, not in WT mice, 24 hours after infection (P<0.005)." (PMID 25700108, 2015). "Lack of significant MyD88 induction by H. pylori may be responsible for infection persistence and induction of endotoxin tolerance, which may lead to a reduced inflammatory response after repeated challenge by LPS." (PMID 25948881, 2015). "Additionally, the induction of IL-12 expression after infection with type I strains did not involve Myd88 signaling, whereas this was clearly Myd88-dependent with type II strains." (PMID 24292064, 2014). "The absence of infection-induced tyrosine nitration in myd88−/− embryos is therefore consistent with the mycobacterial cell wall containing lipoproteins and lipoglycans serving as TLR ligands that stimulate neutrophil iNOS output, either directly or via macrophage signaling." (PMID 24967596, 2014). "Finally, it is interesting to note that STAT3-dependent cytokines, such as IL-6, IL-10, and IL-21, as well as MyD88-dependent IL-1 have been suggested to play a role in memory CD8+ T cell differentiation and functional maturation following immunization and infection." (PMID 24842874, 2014). "The pronounced deficiency in IFN-γ production exhibited by MyD88−/− cells, but not by NLRP3−/− and caspase-1−/− cells, could explain this difference, as IFN-γ−/− mice also succumb early to infection." (PMID 24098823, 2013). "We hypothesized that Toll-like receptor (TLR)-dependent responses are essential for clearance of T. pallidum and, consequently, compared infection in wild-type (WT) mice and animals lacking MyD88, the adaptor molecule required for signaling by most TLRs." (PMID 23940747, 2013). "However, viral titers were significantly increased in the lungs of Myd88−/− mice (p<0.01), but not Tlr3−/− mice 3 days after infection." (PMID 22496659, 2012). "Furthermore, overall lung pathology was only marginally ameliorated in Myd88−/− mice 3 days after infection (data not shown)." (PMID 22496659, 2012). "In addition, we compared infection with wt and ΔcylE GBS in Myd88−/− and Tlr2−/− macrophages." (PMID 22829768, 2012).
infection (continued). "It is likely that Heat-VAC infection of pDCs produces long, uncapped and partially double-stranded viral RNA transcripts that are sensed by the endosomal RNA sensor TLR7, which utilizes its adaptor MyD88 to activate transcription factor IRF7, resulting in the induction of type I IFN." (PMID 22606294, 2012). "In the absence of MyD88, these responses become dysregulated leading to increased bacterial burdens and infection dissemination during acute infection, although it remains to be determined whether these actions are direct or indirect." (PMID 22879997, 2012). "However, transcription of intracellular signalling molecules MyD88, IRAK-1, and TRAF-6 was significantly up-regulated in peritoneal macrophages from mice infected either with P. yoelii 17XL or P. yoelii 17XNL at one, three and five days post-infection." (PMID 22463100, 2012). "Because TLR2 activates the inflammatory state of PMNs in infection and unrestrained inflammation occurred in condition of defective S100B/RAGE axis, we hypothesized that the S100B/RAGE axis may inhibit TLR2/MyD88–driven inflammation to the fungus." (PMID 21423669, 2011). "When an infection occurs, lipopolysaccharides, lipopeptides, microbial DNA, peptide polysaccharides, lipoteichoic acid and other substances can trigger innate immune reactions mediated by Toll-like receptors (TLRs), NOD-like receptors (NLRs), and other relevant molecules, such as MyD88, and so on." (PMID 22023777, 2011). "In a mouse model of infection with vaccinia virus (VV), the most studied member of the poxvirus family, we identified that the Toll-like receptor (TLR) 2-myeloid differentiating factor 88 (MyD88) pathway was critical for the activation of NK cells and the control of VV infection in vivo." (PMID 20300608, 2010). "Mice lacking MyD88 were unable to control the ΔtssK-5 infection and succumbed within 3 days." (PMID 20865170, 2010). "While absence of CCR2 could only affect recruited CD11b+Ly6C+ monocytic cells, absence of IFN-γ and MyD88 signaling can impair the activation of both recruited and resident liver monocytic cells during infection." (PMID 20714353, 2010). "Interestingly, although mice simultaneously lacking TLR2 and TLR9 are highly vulnerable to infection, their mortality rate is still less than that of Myd88−/− mice, pointing to the involvement of other TLRs and/or IL-1/IL-18 in the control of mortality." (PMID 20442858, 2010). "To investigate the importance of MyD88 in SARS-CoV-induced lung inflammation, we employed quantitative RT-PCR (qRT-PCR) to assess mRNA levels of antiviral and proinflammatory cytokine/chemokine gene expression in the infected mouse lung at various times post-infection." (PMID 19079579, 2008). "MyD88 dependent signaling, but not TRIF dependent signaling, contributes to a protective host response against B. pseudomallei at least in part by causing early neutrophil recruitment towards the primary site of infection." (PMID 18946505, 2008). "Interestingly, 100% of IL-1R1- or IL-18R1-deficient mice survived infection by rMA15 (data not shown) indicating that the genetic absence of either receptor did not recapitulate the lethal phenotype observed following infection of MyD88−/− mice." (PMID 19079579, 2008). "In addition, in response to rMA15 infection, MyD88−/− mice failed to upregulate expression of a number of proinflammatory chemokines that promote monocyte recruitment." (PMID 19079579, 2008). "Therefore, to further investigate the role of MyD88 and TRIF in the inflammatory response towards infection with B. pseudomallei, we first measured cytokine levels in whole lung homogenates harvested from WT, MyD88 KO and TRIF mutant mice after intranasal infection with B. pseudomallei." (PMID 18946505, 2008).